MOG (myelin oligodendrocyte glycoprotein)
Diseases named in the same sentence as MOG in open-access papers (continued):
Sharing a sentence is not in itself a finding about the gene and the disease.
experimental autoimmune encephalomyelitis (continued). "We investigated the involvement of AQP4 in disease severity in an established mouse model of experimental autoimmune encephalomyelitis (EAE) produced by immunization with myelin oligodendrocyte glycoprotein (MOG35–55) peptide." (PMID 19660138, 2009). "Experimental autoimmune encephalomyelitis (EAE) induced by myelin oligodendrocyte protein (MOG) in female Dark Agouti (DA) rats is a chronic demyelinating animal model of multiple sclerosis (MS)." (PMID 18501024, 2008). "The animal model of MS, experimental autoimmune encephalomyelitis (EAE) using myelin oligodendrocyte glycoprotein (MOG) peptide residues 35–55 was induced in wildtype C57BL6 mice and in P2x7 deficient mice ('P2x7 mice') that were backcrossed to C57BL6 mice." (PMID 18691411, 2008). "In this study, we characterize the regional, temporal and cellular expression of CCR1, CCR2 and CCR5 mRNA in the spinal cord of rats with myelin oligodendrocyte glycoprotein-induced experimental autoimmune encephalomyelitis (MOG-EAE)." (PMID 17484785, 2007). "Myelin Oligodendrocyte Glycoprotein (MOG)-induced experimental autoimmune encephalomyelitis (EAE) is the most commonly used mouse model for multiple sclerosis (MS)." (PMID 17634104, 2007). "In addition, ARAP-deficient mice presented less severe clinical scores in the myelin oligodendrocyte glycoprotein (MOG)-induced experimental autoimmune encephalomyelitis (EAE)." (PMID 40264755, 2025). "We focused thesestudies on the Myelin Oligodendrocyte Glycoprotein peptide (pMOG35-55)-induced model of experimental autoimmune encephalomyelitis (EAE) in B6 mice, where pMOG38-49/I-Ab-NP therapy can reverse established disease by inducing the formation and expansion of cognate TR1 cells." (PMID 40066448, 2025). "Notably, HCMV UL86 peptide 981–1003 is capable of cross‐reacting with myelin oligodendrocyte glycoprotein peptide 35–55 such that HCMV infection can induce experimental autoimmune encephalomyelitis (EAE) in Lewis rats." (PMID 39698934, 2025). "Furthermore, the absence of the PINK1 and Parkin proteins exacerbates acute inflammation in myelin oligodendrocyte glycoprotein (MOG)-induced experimental autoimmune encephalomyelitis (EAE) in C57BL/6J mice." (PMID 39409029, 2024). "For example, in the mouse model of myelin oligodendrocyte glycoprotein (MOG)-induced experimental autoimmune encephalomyelitis, MOG-reactive T cell clones shared public TCRβ1 that dominated in contacts with pMHC and conferred the receptor with high functional avidity for the antigen." (PMID 37894892, 2023). "Such discrepant findings parallel those in a well-established MS rodent model, namely experimental autoimmune encephalomyelitis triggered by myelin oligodendrocyte glycoprotein (MOG), in which both reduced αS expression, as well as increased levels are reported." (PMID 36785484, 2023). "The work in this paper builds off of previous studies that have shown that co-encapsulation of self-antigen (MOG) and a modulatory cue (rapa) can promote the polarization of antigen-specific regulatory T cells for treatment of pre-clinical model of MS (experimental autoimmune encephalomyelitis)." (PMID 37441198, 2023). "Additionally, we examined the impact of this peptide on MOG-induced experimental autoimmune encephalomyelitis (EAE)." (PMID 37511812, 2023). "The objective of the study was to evaluate if the Cx43 hemichannel blocker, tonabersat, is effective in modulating the inflammatory response and reducing disability in the myelin oligodendrocyte glycoprotein 35–55-induced experimental autoimmune encephalomyelitis (MOG35–55 EAE) model of MS." (PMID 38139284, 2023). "In addition, c-Rel-knockout mice show the potential of resistance to experimental autoimmune encephalomyelitis (EAE) induced by myelin oligodendrocyte glycoprotein (MOG)." (PMID 35514960, 2022).
experimental autoimmune encephalomyelitis (continued). "In addition, EphA4 KO mice show a less severe autoimmune phenotype than WT mice after experimental autoimmune encephalomyelitis (EAE) induction with a MOG peptide." (PMID 36334147, 2022). "In experimental autoimmune encephalomyelitis (EAE) models with mice immunized with MOG, the clinical phenotype depends on the balance between T cells and MOG-Ab titers, where a high cellular component drives an ADEM phenotype, whereas an excess of MOG Abs leads to an optico-spinal disease." (PMID 34997443, 2022). "Experimental autoimmune encephalomyelitis (EAE) resembles the over-activated immune system in MS pathology with specific CD4+ T helper cells response to myelin oligodendrocyte glycoprotein (MOG) antigen, and T cell infiltration, neuroinflammation, demyelination, and hindlimb paralysis." (PMID 35180864, 2022). "In myelin oligodendrocyte glycoprotein (MOG)-induced experimental autoimmune encephalomyelitis (EAE), several areas of demyelination are detectable in mouse cerebral cortex, where neuroinflammation events are associated with scarce inflammatory infiltrates and blood–brain barrier (BBB) impairment." (PMID 36042496, 2022). "Notably, engrafted iOPCs remyelinated the brains of adult shiverer mice and experimental autoimmune encephalomyelitis mice with MOG-induced 14 weeks after transplantation." (PMID 35027563, 2022). "Functionally, using a knock-in mouse model, we found ectopic SKI expression specifically in T cells prevented myelin oligodendrocyte glycoprotein peptide (MOG33–55) induced experimental autoimmune encephalomyelitis (EAE), an animal model of human multiple sclerosis." (PMID 34335622, 2021). "They used the myelin oligodendrocyte glycoprotein (MOG) -induced model of experimental autoimmune encephalomyelitis (EAE) and showed that NOX2-derived macrophages (though interestingly not DCs) were defective in their ability to process and present the I-A(b)-immunodominant peptide of MOG." (PMID 34539670, 2021). "When MOG-induced experimental autoimmune encephalomyelitis was performed in Gas6−/− mice, worse clinical scores, delayed recovery from damage, a higher expression of pro-inflammatory molecules, and a significant increase of macrophages infiltration were observed." (PMID 33347509, 2020). "Although the pathophysiological mechanisms of MOG-antibody associated inflammatory demyelinating disease in humans are so far not fully established, they have been extensively characterized in experimental models of MOG induced experimental autoimmune encephalomyelitis (MOG-EAE)." (PMID 32048003, 2020). "In this study, we showed that Cd226−/− mice were resistant to myelin oligodendrocyte glycoprotein peptide 35-55 (MOG35−55)-induced experimental autoimmune encephalomyelitis (EAE) with highly expressed IL-10+CD4+ T cells and downregulated IL-17A+CD4+ T cells when compared with wild-type (WT) mice." (PMID 32983109, 2020). "Reflecting the function as T cell activator, the development of myelin oligodendrocyte glycoprotein (MOG)-induced experimental autoimmune encephalomyelitis (EAE), an animal model of multiple sclerosis (MS), is improved in Sema4A-deficient mice partly due to impaired Th1 and Th17 differentiation." (PMID 32169103, 2020). "Moreover, significantly lower levels of TSPAN32 were found in encephalitogenic T cells from myelin oligodendrocyte glycoprotein (MOG)-Induced experimental autoimmune encephalomyelitis (EAE) mice." (PMID 31963428, 2020). "Although numerous target autoantigens exist for murine models of MS, myelin oligodendrocyte glycoprotein (MOG) induced experimental autoimmune encephalomyelitis (EAE) appears to have predilections for optic tract pathology and often results in the development of bilateral ON." (PMID 31315675, 2019).
experimental autoimmune encephalomyelitis (continued). "On the contrary, here, we demonstrate that the PNS in myelin oligodendrocyte glycoprotein (MOG)-induced experimental autoimmune encephalomyelitis (EAE), a currently used T-cell mediated model of MS, experiences transient inflammation, cellular injury, and chronic cytoskeletal disruption." (PMID 30957012, 2019). "Experimental autoimmune encephalomyelitis (EAE) induced by myelin oligodendrocyte glycoprotein (MOG) or proteolipid protein (PLP) in mice is the most widely used animal model for the study of MS, which mimics a chronic progression or relapse–remission course of the disease." (PMID 30717494, 2019). "The most common model for studying MS is experimental autoimmune encephalomyelitis (EAE) induced in rodents by active immunization with myelin oligodendrocyte glycoprotein (MOG) because it mimics many of the pathophysiological mechanisms and histopathological features of this disease." (PMID 30484905, 2019). "This also extends to autoantigens, because experimental autoimmune encephalomyelitis (EAE) upon myelin oligodendrocyte glycoprotein (MOG) specific CD4+ T cell transfer is severely attenuated in mice with Atg5 deficiency in dendritic cells and some macrophage populations." (PMID 30542350, 2018). "In this study, we investigated whether SHSST has a beneficial effect in treating myelin oligodendrocyte glycoprotein-induced experimental autoimmune encephalomyelitis (EAE)." (PMID 28458638, 2017). "Hence, we immunized mice with human recombinant myelin oligodendrocyte glycoprotein (rhMOG), which leads to a known B cell- and antibody-dependent experimental autoimmune encephalomyelitis (EAE)." (PMID 29178933, 2017). "With MDA modification being able to enhance the proliferation of autoreactive T cells in vitro, we next addressed whether MOG-MDA would elicit more severe experimental autoimmune encephalomyelitis (EAE) in vivo in wild-type C57BL/6 mice." (PMID 28828577, 2017). "Furthermore, IL-10 was shown to be essential for the protection of C57BL/6 mice from experimental autoimmune encephalomyelitis after administration of the soluble peptide 35–55 from myelin oligodendrocyte glycoprotein." (PMID 28455817, 2017). "Therefore, we investigated the effect of SHSST on neurological symptoms and its cellular biology of myelin oligodendrocyte glycoprotein-induced experimental autoimmune encephalomyelitis (MOG-EAE) mice." (PMID 28458638, 2017). "Moreover, NFAT1 hyperactivation decreased experimental autoimmune encephalomyelitis induced by myelin oligodendrocyte glycoprotein (MOG), a key regulator of CNS myelination." (PMID 27597899, 2016). "Loss of Arg function did not affect development of experimental autoimmune encephalomyelitis, but reduced the number of splenic B-cells in Arg−/− mice following immunization with MOG peptide." (PMID 34527426, 2016). "We investigated whether Hyungbangpaedok-san (HBPDS), a traditional herbal medicine, has a beneficial effect in experimental autoimmune encephalomyelitis (EAE) mice immunized with myelin oligodendrocyte glycoprotein peptide (MOG35-55)." (PMID 26444423, 2015). "Furthermore, recent data have shown that EphA4 knockout mice show a less severe clinical score after Myelin Oligodendrocyte Glycoprotein (MOG)-induced Experimental Autoimmune Encephalomyelitis (EAE) compared with wild-type animals." (PMID 26354550, 2015). "Experimental autoimmune encephalomyelitis in mice, a chronic demyelinating disease of the CNS and a model of multiple sclerosis in humans, is often induced by immunization with myelin oligodendrocyte glycoprotein (MOG)." (PMID 26388873, 2015). "Myelin oligodendrocyte glycoprotein (MOG)-induced experimental autoimmune encephalomyelitis (EAE) in rats is a well-characterized animal model of MS, sharing several important features with the human disease including T helper 1 (Th1) and B-cell involvement, as well as histopathological features." (PMID 23437178, 2013).
experimental autoimmune encephalomyelitis (continued). "One of the first indications for involvement of Th17 in autoimmune diseases came from cytokine replacement studies identifying IL-23, but not IL-12, as a key activator of macrophages in the pathogenesis of myelin oligodendrocyte glycoprotein (MOG) induced experimental autoimmune encephalomyelitis." (PMID 24023564, 2013). "Immunization with myelin oligodendrocyte glycoprotein (MOG) induces experimental autoimmune encephalomyelitis (EAE), a mainly CD4+ T-cell-mediated disease, although CD8+ T cells may play a significant role in demyelination." (PMID 24083230, 2013). "Subsequently, these brain DCs were able to proliferate MOG-specific T cells in the presence of MOG peptide, suggesting its importance in antigen presentation during experimental autoimmune encephalomyelitis (EAE), a demyelinating disease model of multiple sclerosis." (PMID 23102113, 2012). "Myelin oligodendrocyte glycoprotein (MOG) induced experimental autoimmune encephalomyelitis (EAE) is an animal model extensively used to study the pathogenesis of MS by inducing paralytic symptoms, and demyelination in the CNS accompanied by perivascular mononuclear cell infiltration." (PMID 22563398, 2012). "Myelin oligodendrocyte glycoprotein (MOG)-induced experimental autoimmune encephalomyelitis (EAE) is a well characterized animal model of MS, sharing several important features including T helper 1 (Th1), Th17 and B-cell involvement as well as histopathological characteristics." (PMID 22815714, 2012). "These mice display a constitutive expression of NF-κB proteins in macrophages and monocytes, but no spontaneous myelopoetic phenotype thus allowing for studying the role of this transcription factor in myelin-oligodendrocyte-glycoprotein induced experimental autoimmune encephalomyelitis (MOG-EAE)." (PMID 22260436, 2012). "To address this question we investigated the fate of transplanted SCs in myelin oligodendrocyte glycoprotein (MOG)-induced experimental autoimmune encephalomyelitis (EAE) in the Dark Agouti rat; an animal model that reproduces the complex inflammatory demyelinating immunopathology of MS." (PMID 22984406, 2012). "We study the genetic regulation of myelin oligodendrocyte glycoprotein (MOG) induced experimental autoimmune encephalomyelitis (EAE) in rats due to a close mimicry with MS, with a protracted relapsing disease course, inflammatory infiltrates, prominent demyelination and axonal damage." (PMID 20856809, 2010). "One of the most abundant and relevant MFGM protein is butyrophilin, a protein having effects on modulation of the encephalitogenic T-cell response to myelin oligodendrocyte glycoprotein (MOG), related to human multiple sclerosis, recently reported in experimental autoimmune encephalomyelitis (EAE)." (PMID 22253986, 2009). "To specify markers of the chronic disease phase, we performed proteome profiling during the later phase of myelin oligodendrocyte glycoprotein induced experimental autoimmune encephalomyelitis (MOG-EAE, day 35 after immunization) as a model disease mimicking many aspects of secondary progressive MS." (PMID 19865482, 2009). "Similarly, using the myelin oligodendrocyte glycoprotein (MOG)-induced experimental autoimmune encephalomyelitis (EAE) model, it has been shown that TNFα KO mice developed more severe EAE, while TNFα treatment ameliorated the disease." (PMID 18380898, 2008). "The results demonstrate that AE, when modified with myelin oligodendrocyte glycoprotein (MOG) peptide (AE/M), can confer antigen‐specific immune tolerance and promote regulatory T cells (Treg), thereby protecting mice from inflammatory symptoms in the experimental autoimmune encephalomyelitis model." (PMID 39937659, 2025).
experimental autoimmune encephalomyelitis (continued). "Indeed, encephalitogenic T cells from Myelin Oligodendrocyte Glycoprotein (MOG)-induced Experimental Autoimmune Encephalomyelitis (EAE) mice—a widely used model for MS—exhibited markedly reduced TSPAN32 expression alongside increased levels of tetraspanins CD9, CD53, CD82, and CD151." (PMID 39858501, 2025). "However, MOG has been established as an antigenic target in animal models of experimental autoimmune encephalomyelitis, and relevant studies proposed that MOG antibodies are involved in the pathogenesis of inflammatory demyelinating disease as revealed by animal models." (PMID 36688157, 2022). "Furthermore, 3xAire‐KI females showed higher scores of experimental autoimmune encephalomyelitis induced by myelin oligodendrocyte glycoprotein than wild‐type littermates, suggesting that augmented Aire expression exacerbates organ‐specific autoimmunity under disease‐prone conditions." (PMID 35313042, 2022). "Interestingly, a higher disease severity was observed in wildtype mice in the late afternoon compared to other time points, weeks after induction with myelin oligodendrocyte glycoprotein (MOG) to induce experimental autoimmune encephalomyelitis (EAE), a mouse model of multiple sclerosis." (PMID 31931006, 2020). "In experimental autoimmune encephalomyelitis (EAE), an immune response initially targeting a myelin protein (e.g., myelin oligodendrocyte glycoprotein, MOG) later spreads to other myelin components (MBP, PLP)." (PMID 40528008, 2025). "In 2013–2015, the main keywords were MS, OCT, MOG, NMO, retinal ganglion cells, experimental autoimmune encephalomyelitis, autoimmune diseases, plasma exchange (PE) and clinical isolated syndrome." (PMID 38342798, 2024). "MOG itself, the target of MOG-IgG, was well known long before the discovery of MOGAD as the protein used to prepare experimental autoimmune encephalomyelitis (EAE) rodents as a model for MS." (PMID 38468222, 2024). "Experimental autoimmune encephalomyelitis (EAE) is an animal model of inflammatory demyelinating disease characterized by the primary and secondary production of MOG-specific lymphocytes and MOG antibodies." (PMID 39267735, 2024). "In experimental autoimmune encephalomyelitis (EAE), ablation of meningeal lymphatic drainage ameliorates EAE (spontaneous) pathology by limiting the drainage of MOG into dCLNs, thereby preventing the activation of MOG-specific T cells." (PMID 38287311, 2024). "Exacerbated experimental autoimmune encephalomyelitis (EAE) symptoms and delayed recovery were manifested in MOG-immunized GLK Tg mice, suggesting a decreased suppressive function of EAE-induced Treg cells in Lck-GLK Tg mice." (PMID 35966593, 2022). "In experimental autoimmune encephalomyelitis (EAE), a mouse model of MS, induction of autoreactive B cell responses against myelin oligodendrocyte glycoprotein (MOG) requires the presence of the microbiota." (PMID 35572569, 2022). "In this study, we explored the in vivo treatment of experimental autoimmune encephalomyelitis (EAE), a model for multiple sclerosis (MS) induced in mice immunized with MOG using the PDE8-selective inhibitor PF-04957325." (PMID 35203312, 2022). "Experimental autoimmune encephalomyelitis (EAE), induced by myelin oligodendrocyte glycoprotein (MOG), is an animal model used widely for multiple sclerosis (MS), characterized by central nervous system (CNS) inflammation, demyelination, and axonal damage." (PMID 36042496, 2022). "In experimental autoimmune encephalomyelitis, CD8+CD28- Tregs inhibited the secretion of IFN-g by myelin oligodendrocyte glycoprotein-specific CD4+ T cells." (PMID 34335631, 2021). "Since MOG-reactive CD4+ T cells are the most important cell type for the induction of the neuroinflammatory disease experimental autoimmune encephalomyelitis (EAE), we examined the influence of MOG-expression on CD4+ T cell tolerance." (PMID 34149706, 2021).